FDCSP (follicular dendritic cell secreted protein)
Description:
Can bind to the surface of B-lymphoma cells, but not T-lymphoma cells, consistent with a function as a secreted mediator acting upon B-cells.
Synonyms: FDC-SP; C4orf7
Tractability: Antibody: UniProt places it where antibodies can reach, with medium confidence; UniProt predicts a signal peptide or a membrane-spanning region; its Gene Ontology location is reachable by antibodies, with medium confidence.
Gene: Protein-coding gene on chromosome 4 (70,226,124 to 70,235,252, forward strand). Ensembl gene ENSG00000181617.
Subcellular location: Secreted
Gene Ontology:
Molecular function: protein binding
Cellular component: extracellular region
Genetic constraint (gnomAD): Loss-of-function variants: 2 observed, 3.46 expected, observed/expected ratio (o/e) 0.58, 90% interval 0.23 to 1.63. That is too few expected variants to judge how well the gene tolerates losing a copy. Missense variants: 70 observed, 74.6 expected, observed/expected ratio (o/e) 0.94, 90% interval 0.77 to 1.14. Synonymous variants: 21 observed, 24.34 expected, observed/expected ratio (o/e) 0.86, 90% interval 0.61 to 1.24.
Homologues: Orthologues: chimpanzee FDCSP (99% identical), macaque FDCSP (80% identical), pig FDCSP (58% identical), dog FDCSP (53% identical), rabbit FDCSP (53% identical), mouse Fdcsp (45% identical), rat Fdcsp (41% identical).
Diseases named in the same sentence as FDCSP in open-access papers:
FDCSP is named in the same sentence as 29 diseases in open-access papers, as found by Europe PMC text mining. Sharing a sentence is not in itself a finding about the gene and the disease. The quoted sentences say what the papers report.
breast carcinoma (3 papers, 2020 to 2025). "LINC02188 has been shown to be upregulated in triple-negative breast cancers, while PROM1, ROPN1, GABRP, and FDCSP were previously associated with a cancer stem cell signature in a basal-like breast cancer phenotype." (PMID 33525353, 2021). "Other selected genes, SLC40A1, ADAMTS15, THSD4, GREB1, and SLC44A4 have been reported to be related to breast cancer, and ZG16B, FDCSP, and SRARP have been associated with other types of tumors." (PMID 32795265, 2020). "We also identified two genes, epidermal growth factor-like domain-containing protein 6 (EGFL6) and follicular dendritic cell secreted protein (FDCSP), which were highly down-regulated after treatment with metformin compared to placebo in postmenopausal breast cancer survivors." (PMID 40374694, 2025).
follicular dendritic cell sarcoma (2 papers, 2017 to 2022). A neoplasm composed of spindle to ovoid cells which have morphologic and immunophenotypic characteristics of follicular dendritic cells. "Immunohistochemistry on follicular dendritic cell sarcomas for FDCSP was positive in sixteen cases (16/22, 72.73%) with either an intense and diffuse cytoplasmic staining or a prevailing perinuclear positivity." (PMID 28145886, 2017). "It is worth mentioning that follicular dendritic cell sarcoma (FDCS), a disease characterized by the malignant proliferation of FDCs itself, exhibits overexpressed FDCSP and overexpressed CXCL13, which cooperate with other genes to diagnose FDCS." (PMID 36291667, 2022).
melanoma (2 papers, 2017 to 2023). A malignant, usually aggressive tumor composed of atypical, neoplastic melanocytes. "In order to test the specificity of FDCSP and SRGN in FDC-S diagnosis we stained 87 soft tissue tumors, 5 thymomas, 5 melanomas, 3 interdigitating dendritic cell sarcomas and 114 carcinomas." (PMID 28145886, 2017). "No reactivity for FDCSP and SRGN was detected on melanomas, thymomas or carcinomas." (PMID 28145886, 2017).
ovarian carcinoma (2 papers, 2014 to 2025). A malignant neoplasm originating from the surface ovarian epithelium. "Several studies reported that FDCSP is overexpressed in several types of cancer, including breast and ovarian cancers, and contributes to cancer progression and aggressiveness." (PMID 40900789, 2025).
B-cell lymphomas (1 paper, 2025). "Top proteins specifically associated with germinal center-derived B-cell lymphoma risk included LSAMP, FDCSP, SERPINA9, CCL21 and CD40LG." (PMID 40894013, 2025).
dendritic cell sarcoma (1 paper, 2017). A sarcoma that involves the dendritic cell. "Notably, one case of interdigitating dendritic cell sarcoma expressed FDCSP in about 40% of neoplastic cells while it was negative for SRGN and other FDC markers." (PMID 28145886, 2017).
head and neck cancer (1 paper, 2022). A primary or metastatic malignant neoplasm affecting the head and neck. "The expression levels of FDCSP in head and neck cancer patients with different HPV statuses from the TCGA HNSC database were analyzed by TIMER." (PMID 36291667, 2022).
hidradenitis suppurativa (1 paper, 2025). A chronic suppurative and cicatricial disease of the apocrine glands occurring chiefly in the axillae in women and in the groin and anal regions in men. "The LTo gene program (including CXCL13 and FDCSP) was not expressed in healthy adult skin but could be upregulated in specific skin diseases, particularly hidradenitis suppurativa." (PMID 40993240, 2025).
lung adenocarcinoma (1 paper, 2024). A carcinoma that arises from the lung and is characterized by the presence of malignant glandular epithelial cells. "Further analysis based on TCGA database showed that FDCSP was also highly expressed in lung adenocarcinoma, indicating its potential role in the occurrence and development of pulmonary nodules." (PMID 39043808, 2024).
lung squamous cell carcinoma (1 paper, 2023). "In lung squamous cell carcinoma, the up-regulated FDCSP was strongly enriched for the positive regulation of immune processes and inflammatory responses." (PMID 36968579, 2023).
mesenchymal tumors (1 paper, 2017). "In conclusion, by a combined approach of next generation sequencing and high throughput immunohistochemistry we identified two novel markers for FDC-S, FDCSP and SRGN, and suggested a highly effective and ready-to-use approach for its differential diagnosis with other mesenchymal tumors." (PMID 28145886, 2017). "In our cohorts CXCL13, CD21, CD35, FDCSP and SRGN were the best markers for FDC-sarcoma diagnosis and could discriminate 21/22 FDC sarcomas from other mesenchymal tumors by linear discriminant analysis." (PMID 28145886, 2017).
Niemann-Pick disease, type C1 (1 paper, 2012). Type C Niemann-Pick disease associated with a mutation in the gene NPC1, encoding Niemann-Pick C1 protein. "Three known genes, TLR4 interactor with leucine rich repeats (TRIL), Niemann-Pick disease, type C1, gene-like 1 (NPC1L1), and C4orf7 also termed follicular dendritic cell secreted protein were selected by three of the four methods." (PMID 22606341, 2012).
oropharyngeal cancer (1 paper, 2022). Carcinoma, predominantly squamous cell, arising from the epithelial cells of the oropharynx. "In either 3 samples of oropharyngeal cancer tissues collected, the protein expression levels of FDCSP and CXCL13 were both higher in HPV+ cancer tissues." (PMID 36291667, 2022).
periodontitis (1 paper, 2017). An acute or chronic inflammatory process that affects the tissues that surround and support the teeth. "Therefore, progression of periodontitis induces the expression of FDCSP and ODAM." (PMID 28560203, 2017). "The levels of FDCSP and ODAM mRNA appear to be increased in periodontitis." (PMID 28560203, 2017).
renal carcinoma (1 paper, 2023). A carcinoma arising from the epithelium of the renal parenchyma or the renal pelvis. "As immunological responses are linked to FDCSP, we hypothesize that it could be used as an immune-related prognostic marker for renal cancer." (PMID 36899339, 2023). "Therefore, it is necessary to study the role of FDCSP in the occurrence and development of renal cancer." (PMID 36899339, 2023).
soft tissue tumors (1 paper, 2017). "FDCSP was expressed by two soft tissue tumors, one sinonasal haemangiopericytoma (SNHP-1) and one synovial sarcoma (SS-2); SRGN was negative in all." (PMID 28145886, 2017).
viral infection (1 paper, 2022). "Based on gene function and viral infection, we focused on FDCSP, a gene strongly associated with immune cells." (PMID 36291667, 2022).
cancer (8 papers, 2014 to 2025). A tumor composed of atypical neoplastic, often pleomorphic cells that invade other tissues. "At the gene level, FDCSP (cancer cell migration and invasion), KIR2DL3 (immune response), SLC30A10 (antiapoptotic), MAB21L2, PCDH9 (cell adhesion), PEG3 (cell proliferation) were found to be highly expressed in the Lymph-node (LN)-positive samples." (PMID 37377901, 2023).
tumor (7 papers, 2017 to 2025). "Since the FDCSP gene is known to be closely related to the immune function of tumor tissue, immune infiltration of tumors was analyzed and correlated with the level of FDCSP expression (high and low)." (PMID 38994960, 2024). "FDC secreted protein (FDCSP) and Serglycin (SRGN) proved to be specific markers of FDC and related tumor." (PMID 28145886, 2017). "In order to identify the key regulators in the ICD risk subgroups, first we verified the mRNA expression levels of these eight genes, and we found that only SFTPB and SERPIND1 were highly expressed in normal tissues, whereas FAM83A, FDCSP, KRT6A, RHOV and TPX2 were highly expressed in tumor tissues." (PMID 39247599, 2024). "Notably, all the correctly classified FDC-S cases were positive for at least two markers among CXCL13, CD21, CD35, FDCSP and SRGN; this information could be easily applicable in the routine diagnosis of this tumor." (PMID 28145886, 2017).
FDCSP also shares sentences with these, for which no sentence is quoted: lung carcinoma (2 papers); leukemia (1); lymphoma (1); non-small cell lung carcinoma (1); prostate carcinoma (1); renal cell carcinoma (1); sarcoma (1); synovial sarcoma (1); thymoma (1); triple-negative breast carcinoma (1).